NPIPA9 (nuclear pore complex interacting protein family member A9)
Gene: Protein-coding gene on chromosome 16 (18,358,086 to 18,379,331, reverse strand). Ensembl gene ENSG00000233024.
Subcellular location (Human Protein Atlas): Nucleoplasm
Homologues: Paralogues in human: NPIPA6 (100% identical), NPIPA7 (99% identical), NPIPA8 (99% identical), NPIPA5 (94% identical), NPIPA1 (94% identical), NPIPA2 (88% identical), NPIPA3 (88% identical), NPIPB2 (73% identical), NPIPB12 (70% identical), NPIPB13 (70% identical), NPIPB4 (69% identical), NPIPB5 (69% identical), and 7 more.